MAP3K1 (mitogen-activated protein kinase kinase kinase 1)
Diseases named in the same sentence as MAP3K1 in open-access papers (continued):
Sharing a sentence is not in itself a finding about the gene and the disease.
cancer (continued). "MAP3K1 mutations predict response to mitogen-activated protein kinase kinase (MEK) and phosphoinositide 3-kinase (PI3K) inhibitors, with mutant cancers showing higher MEK inhibitor response than wild-type tumors." (PMID 41972694, 2026). "The Map3k1TG model represents a powerful tool for investigating developmental and disease-related processes driven by MAP3K1 hyperactivation, including cancer, congenital disorders, and epithelial pathologies." (PMID 40558521, 2025). "We then confirmed the downregulation of TAP1/2 expression in Map3k1-mut cancer cells compared with Map3k1-WT cancer cells in the coculture system by quantitative PCR with reverse transcription (RT–qPCR) analysis and Western blot assay." (PMID 39531335, 2024). "To investigate the potential functions of MAP3K1 in cancer development, we initially examined its expression in different types of human cancer." (PMID 39443331, 2024). "Five genes were implicated in the development of other cancer types: SRGAP2C, MAP3K1, FGFR2, LSP1, and FMNL3." (PMID 36703164, 2023). "Given the potential impact of MAP3K1 rs889312 SNP on the prognosis of various cancers, this meta‐analysis was performed to obtain solid and credible evidence." (PMID 36560873, 2023). "As cancers that have lost MAP3K1 or MAP2K4 fail to activate JNK, loss-of-function mutations in MAP3K1 or MAP2K4 confer sensitivity to MEK inhibition, as shown in cell cultures and patient-derived xenograft (PDX) models." (PMID 36358725, 2022). "TBX3 is a transcription factor frequently overexpressed in various types of human cancers, including BC, while the MAP3K1 gene induces MAP-kinase pathway." (PMID 35637532, 2022). "The cancer genome spectrum showed sarcomatoid HCC group had significant higher mutation rates in CDKN2A, EPHA5, FANCM and MAP3K1." (PMID 34331411, 2021). "The MAP3K1 gene is the most important member in the MAPK signal pathway which activates the transcription of essential cancer genes." (PMID 30285756, 2018). "Recently, we showed that cancers that fail to activate JNK-JUN, due to inactivating mutations in upstream kinases MAP3K1 and MAP2K4, are sensitive to MEK inhibition." (PMID 30482246, 2018). "Numerous mouse and human genetic analyses have demonstrated that Map3k1 is of critical importance for the immune system, cardiac tissue, testis, wound healing, tumorigenesis and cancer." (PMID 25613373, 2015).
cancer (continued). "In vitro studies using genetic gain- and loss-of-function approaches have identified diverse and cell type-specific roles for MAP3K1 in the regulation of cell survival or apoptosis, cytoskeletal dynamics, migration, stem cell maintenance and differentiation, and cancer metastasis." (PMID 40558521, 2025). "We first assessed the effect of Map3k1 gene itself on cancer cells and discovered that Map3k1-WT significantly promoted cell proliferation in vitro, which is consistent with previously reported researches, while Map3k1-mut abolished this promoting effect." (PMID 39531335, 2024). "To date, increasing evidence has indicated that MAP3K1 is involved in the progression of cancers." (PMID 39443331, 2024). "At present, the role of MAP3K1 in cancer cell proliferation and death is still controversial." (PMID 39443331, 2024). "The critical function of MAP3K1 in cell fate decisions suggests that it may be a target for deregulation in cancer." (PMID 38398215, 2024). "57×10-122), and the mapped gene MAP3K1 regulates apoptosis, survival, migration, differentiation, and other functions, which suggests that it may be a target for cancer treatment." (PMID 36819030, 2023). "The MAP3K1 gene has a pivotal role in the MAPK‐dependent signaling mechanism that regulates the transcription of vital neoplastic genes, and the link between unregulated MAPK‐associated pathways with cancer has already been established." (PMID 36560873, 2023). "Above results suggest that MAP3K1 is involved in cancer development." (PMID 34404765, 2021). "Our results indicate that MAP3K1 may also function as a downstream effector of other modulators, including lncRNA, to play a role in cancer cell proliferation." (PMID 34404765, 2021). "This might be due to mutations in MAP3K14/NIK or MAP3K1/MEKK1 of TE617.T cells, which result in an alternative splice variant or a threonine deletion at position 949, respectively (The Cancer Cell Line Encyclopedia)." (PMID 34172934, 2021). "Further analysis of WES data revealed additional variants in common cancer‐related genes involved in DNA replication and DNA damage (e.g., ATM, CDKN1A), cell polarization (SCRIB), proliferation (RNASEL), VEGF expression (MAP3K1, MAP3K6), and in genes encoding growth factors (FGF2) (Table EV2)." (PMID 32667137, 2020). "Cancers that have lost MAP3K1 or MAP2K4 fail to activate JNK-JUN." (PMID 29795445, 2018). "More importantly 9 new cancer genes were identified; seven of them (ARID1B, CASP8, MAP3K1, MAP3K13, NCOR1, SMARCD1, CDKN1B) carried truncating mutations and were characterized by biallelic inactivation, suggesting that they were potentially recessive cancer susceptibility genes." (PMID 26561834, 2015). "The MAP3K1 gene encodes MAP3K1, a serine/threonine kinase protein, which is involved in the MAPK signaling pathway and plays a pivotal role in regulating transcription of important cancer genes." (PMID 24759887, 2014). "MAP3K1 encodes a MEK kinase involved in the regulation of cell proliferation, SCARB1 plays an important role in the regulation of cell homeostasis by maintaining the level of cholesterol available in fibroblasts for androgen synthesis, and S100A10 controls migration of cancer-associated macrophages." (PMID 35740605, 2022). "The high degree of interaction observed in genes like MAPK3, MAP3K1, SRC, and RAF1 further supports their roles in regulating cellular signaling, which is crucial for understanding cancer biology and therapeutic resistance." (PMID 40136517, 2025).
cancer (continued). "Among the MAP3K family members, MAP3K1, MAP3K4, and MAP3K5 have garnered considerable attention in the context of GC due to their established roles in cancer biology and signaling pathways relevant to gastric tumorigenesis." (PMID 39901302, 2025). "KMT2D and GATA3 were uniquely identified in African Americans as cancer drivers reported in TCGA data, whereas PIK3CA, MAP3K1, CDH1, and MUC6 were identified in Caucasians." (PMID 37454130, 2023). "The new cancer genes so identified were AKT2, ARID1B, CASP8, CDKN1B, MAP3K1, NCOR1, SMARCD1, and TBX3." (PMID 32210163, 2020). "Here we identify a previously unrecognized cross-talk between the PI3Kα and MAP3K1/JNK pathway and demonstrate its potential impact in cancer therapy resistance." (PMID 29765551, 2018). "Our data also predict that inhibitors of the MAP3K1, MAP2K4 or JNK kinases should also show synergy with MEK inhibition in a variety of cancers." (PMID 29795445, 2018). "The most apparent function of MAP3K1 is to phosphorylate and activate MAPK kinase (MAPK2), which in turn phosphorylates MAPK/ERK to produce downstream signaling effects on a variety of cancer genes." (PMID 24759887, 2014). "Moreover, disruption of α2 integrin, MAP3K1, MAPK11, PPP2R1A, and NHE1-mediated ECM internalisation significantly impaired cancer cell migration and invasion in 2D and 3D culture systems." (PMID 39666682, 2024). "PIK3CA, CBFB, CDC27, MAP3K1, and ESRRA were among the genes that were cancer drivers." (PMID 37454130, 2023). "MAP3K1 regulates JNK activation and is altered in a variety of cancer types." (PMID 26325386, 2015). "Mutations of MAP3K1, which were previously associated with low ICR in breast and pan-cancer TCGA analysis, were the only ones with a negative correlation with ICR score in both hypermutated and non-hypermutated cancers in AC-ICAM." (PMID 37202560, 2023). "In addition to the potential for combinatorial targeting of CDKN2A and MAP3K1, two over-expressed druggable proteins residing within this central component of the network were found to interact with more than one CIS-derived candidate cancer protein." (PMID 34154646, 2021).
infection (21 papers, 2007 to 2025). The state of being infected such as from the introduction of a foreign agent such as serum, vaccine, antigenic substance or organism. "These activating signals may counteract or overcome the inhibitory action of 22–25 VSV, such that it is possible for MAP3K1 activation to increase over time even during 22–25 VSV infection." (PMID 35108303, 2022). "At 24 h after infection, the following genes were upregulated in infected macrophages transfected with the let-7e inhibitor compared to macrophages transfected with NC: Tlr7, Ly96/MD-2, Casp8, Map3k1, Mapk8, Ptgs2/Cox2, Csf 3/GCSF, and the ubiquitin-conjugating enzyme E2N (Ube2n)." (PMID 30555476, 2018). "4T1 cells were infected with control virus or Map3k1 amiRNA virus and subjected to real-time PCR analysis to determine the level of MAP3K1 mRNA in the cells, which indicated that the level of MAP3K1 mRNA was apparently decreased after the infection of Map3k1 amiRNA virus (Data not shown)." (PMID 26759750, 2016).
benign tumours (1 paper, 2018). "Important upstream regulators in our study, unique to benign tumours were AREG, TLR2, TGF1B, HGF, MAP3K1." (PMID 30517191, 2018).
MAP3K1 also shares sentences with these, for which no sentence is quoted: lung cancer (9 papers); bacterial infection (3); viral infection (3); acute myeloid leukemia (2); Autoimmunity (2); diabetes (2); influenza (2); invasive breast carcinoma (2); leukemia (2); prostate tumors (2); retinal degeneration (2); triple-negative breast carcinoma (2); acute promyelocytic leukemia (1); anaplastic oligoastrocytoma (1); androgen insensitivity syndrome (1); asthma (1); astrocytomas (1); bladder cancer (1); bovine tuberculosis (1); campomelic dysplasia (1); cardiac ischemia (1); cervical cancer (1); Chagas disease (1); chondrosarcoma (1); choriocarcinoma (1); colitis (1); colon adenocarcinoma (1); colorectal adenocarcinoma (1); colorectal tumors (1); congenital hypogonadotropic hypogonadism (1).
A further 37 diseases each share a sentence with MAP3K1 in 1 paper.